BRD9 (bromodomain containing 9)
Diseases named in the same sentence as BRD9 in open-access papers (continued):
Sharing a sentence is not in itself a finding about the gene and the disease.
adrenocortical tumors (1 paper, 2024). "Among other DEPs, several have known roles in cancer (e.g. Dad1 and Brd9), adrenocortical tumors (Gnas), and cytochrome c oxidase subunits (e.g. Cox6c2 and Cox7a2l)." (PMID 38864697, 2024).
cervical squamous cell carcinoma (1 paper, 2024). A squamous cell carcinoma arising from the cervical epithelium. "When any of the m6A readers (IGF2BP2 and IGF2BP3) or m6A writer METTL3 were mutated, BRD9 was significantly highly expressed in cervical squamous cell carcinoma and endocervical adenocarcinoma (CESC), BRCA and LUAD." (PMID 38303608, 2024).
colitis (1 paper, 2021). Inflammation of the colon. "Evidence for the importance of BRD9 in immune function has come from studies in the T cell transfer colitis model, where T effector cells were co-transferred with either BRD9-depleted or normal Treg cells." (PMID 33922725, 2021). "Notably, BRD9-deficient Tregs, unlike control Tregs, failed to prevent colitis development in recipient mice." (PMID 33922725, 2021).
colorectal adenocarcinoma (1 paper, 2024). The most common type of colorectal carcinoma. "I-BRD9 also blocked colorectal adenocarcinoma tumor growth through a mechanism that involves the regulation of glycolytic gene expression by BRD9." (PMID 38390898, 2024).
Cri-du-chat syndrome (1 paper, 2022). Monosomy 5p, also known as Cri du chat syndrome, is a rare autosomal deletion syndrome characterized by a mewing cry (cri du chat) in infancy, multiple congenital anomalies, intellectual disability, microcephaly, and facial dysmorphism. "BRD9 has in fact been shown to regulate EZH2 expression by binding together with CTCF in an EZH2 enhancer, but we do not know if EZH2 expression changes contribute to Cri du chat syndrome pathogenesis." (PMID 36242045, 2022).
dyslipidemia (1 paper, 2025). "BRD9 inhibitors can thus have therapeutic potential for the treatment of dyslipidemia, MASLD, and MASH." (PMID 40780491, 2025). "Thus, BRD9 could be considered a novel pharmacological target for dyslipidemia." (PMID 40780491, 2025).
gastrointestinal stromal tumor (1 paper, 2022). "BRD9 is overexpressed in many malignancies, including CRC and Gastrointestinal Stromal Tumors (GISTs)." (PMID 36297001, 2022).
hearing loss (1 paper, 2020). "Similar to ARHGEF40 and BRD9, the function of CDH23 has not been established hitherto in spite of being implicated in Usher syndrome type ID and non-syndromic hearing loss." (PMID 32276436, 2020).
lentivirus infection (1 paper, 2023). Virus diseases caused by the Lentivirus genus. "To thoroughly understand the underlying mechanisms that BRD9 exerts in COAD tumorigenesis, we firstly utilized the lentivirus infection methods to generate BRD9‐overexpressing COAD cells (SW620 and HCT‐8), which were verified by western blot." (PMID 35778964, 2023). "As expected, BRD9 deficiency remarkably suppressed the SW620 cell growth ability in the 3D soft agar, whereas, BRD9 restoration via lentivirus infection technology could completely rescue the impaired colony formation ability." (PMID 35778964, 2023).
mesothelioma (1 paper, 2024). A usually malignant and aggressive neoplasm of the mesothelium which is often associated with exposure to asbestos. "The BRD9/SMARCD1 axis exhibited promising discriminative performance in forecasting the prognosis of patients afflicted with liver hepatocellular carcinoma (LIHC) and mesothelioma." (PMID 38303608, 2024).
metastatic disease (1 paper, 2021). "BRD9 has most potential as a diagnostic biomarker and drug target in metastatic disease." (PMID 34944438, 2021).
mucosal melanoma (1 paper, 2022). A melanoma that arises from a mucosal site. "SF3B1 is involved in RNA splicing, and the hotspot mutation recurrent in mucosal melanoma changes the splicing of several cancer genes, including the non-canonical BAF complex member BRD9." (PMID 35706047, 2022).
Obesity (1 paper, 2020). Accumulation of substantial excess body fat. "We attempted to explain the cause of obesity in Nur77 knockout mice from the perspective of the gut microbiota and to investigate the inhibitory effect of calcipotriol combined with BRD9 inhibitor (iBRD9) on obesity." (PMID 32203112, 2020).
osteoporosis (1 paper, 2023). A condition of reduced bone mass, with decreased cortical thickness and a decrease in the number and size of the trabeculae of cancellous bone (but normal chemical composition), resulting in increased fracture incidence. "Interestingly, although carrying osteoporosis phenotype (asterisks), the Brd9-depleted mouse showed resistant to LPS/ligation-stimulated local acute damage on the periodontal alveolar bone and osteoclast activity compared with the control mice." (PMID 36918560, 2023).
Pancytopenia (1 paper, 2024). An abnormal reduction in numbers of all blood cell types (red blood cells, white blood cells, and platelets). "While in murine hematopoietic system expression of Brd9 in LSK and HSC population is significantly lower than B cells, the knockout mice still show a pancytopenia, and myeloid lineage skewing with most severe effects on B cell development." (PMID 38816579, 2024).
paraganglioma (1 paper, 2024). A benign or malignant neoplasm arising from paraganglia located along the sympathetic or parasympathetic nerves. "BRD9 expression was positively related with MSI in bladder urothelial carcinoma (BLCA), LUAD, LUSC, SARC and STAD, and negatively related with that in DLBC and pheochromocytoma and paraganglioma (PCPG)." (PMID 38303608, 2024).
prostate adenocarcinoma (1 paper, 2024). "We observed increased methylation levels of BRD9 in BRCA, KIRC and KIRP, and conversely reduced methylation levels in BLCA, ESCA, HNSC, LIHC, LUAD, LUSC, PAAD, prostate adenocarcinoma (PRAD), READ and UCEC." (PMID 38303608, 2024).
testicular germ cell tumours (1 paper, 2024). "CNA of BRD9 was particularly pronounced in testicular germ cell tumours (TGCT), where copy number deep deletion made up all the genetic alterations to BRD9 in that particular cancer." (PMID 38303608, 2024).
type 2 diabetic (1 paper, 2019). "They showed that the interaction of BRD7 with VDR ultimately leads to inhibition of BRD9 activity in β cells, which in turn reverses β cell dysfunction and reduces blood glucose levels in type 2 diabetic mouse models." (PMID 30926848, 2019).
Uterine leiomyoma (1 paper, 2022). The presence of a leiomyoma of the uterus. "The constitutive (basal) expression levels of BRD9 in cell lines from human uterine smooth muscle (UTSM), human uterine leiomyoma (HuLM), and two different uLMS (SK-UT-1 and MES-SA) were evaluated by Western blot analysis." (PMID 35883603, 2022).
uterine sarcoma (1 paper, 2022). "This analysis revealed that the expression levels of BRD9 exhibited a graded increase from normal and benign tumors to malignant uterine sarcoma cells." (PMID 35883603, 2022).
virus infection (1 paper, 2022). "Our evaluation of BRD9 genetic variants has now identified that severely truncated ultra-rare BRD9 LOF alleles exist in the human population, and revealed that under conditions where only these alleles are present there is compromised ability of IFN to fully protect cells against virus infection." (PMID 36100643, 2022).
cancer (83 papers, 2016 to 2025). A tumor composed of atypical neoplastic, often pleomorphic cells that invade other tissues. "These pan‐cancer study revealed the diagnostic and prognostic potential, along with the biological mechanism of BRD9 as a novel therapeutic target in human tumours." (PMID 38303608, 2024). "While mutations of SWI/SNF components are observed in cancers, the mutation frequency in hematological malignancies, in particular of BRD9, is rare compared to solid tumors." (PMID 38816579, 2024). "Taken together, our pan‐cancer study revealed the diagnostic and prognostic potential, as well as the biological mechanism of BRD9 as a novel therapeutic target in human tumours for the first time." (PMID 38303608, 2024). "Loss-of-function mutations in the gene encoding BRD9 are rare; the BRD9 gene is amplified in multiple cancers and is considered an oncogene in some of them." (PMID 38390898, 2024). "BRD9 is essential for the proliferation of SMARCB1-deficient cancer cell lines and is therefore a therapeutic target for these lethal cancers, and it is also a key target for causing acute myeloid leukemia." (PMID 36733714, 2023). "Previous studies reported that correcting the error splicing of BRD9 (a tumor suppressor) in cancer cells bearing SF3B1 mutations effectively inhibited tumor growth." (PMID 35252202, 2022). "More recently, the BRD9 subunit of the ncBAF complex was identified as a synthetic lethal target in SNF5-deficient cancers and was found to maintain gene expression in these cancers." (PMID 35650187, 2022). "Overall, targeting BRD7/9 with conventional BRD inhibitors failed to fully recapitulate the phenotypic response of genetic BRD9 knockout studies in SMARCB1-deficient cancers." (PMID 33941852, 2021). "The first example to illustrate this issue are the SMARCB1-deficient cancers that are sensitive to depletion of the ncBAF subunit BRD9." (PMID 33941852, 2021). "The literature suggests that BRD9 plays an oncogenic role in many cancers with promise both as a diagnostic and prognostic biomarker." (PMID 34944438, 2021). "Previous studies have reported that BRD9 is required for the survival of some cancer types, particularly cancers with mutations that affect polybromo-associated BAF and canonical BAF6." (PMID 32905346, 2020). "BRD9 is essential for the proliferation of SMARCB1-deficient cancer cell lines, suggesting it as a therapeutic target for these lethal cancers." (PMID 31015438, 2019). "BRD9 inhibition by I-BRD9 in Kasumi-1 cells resulted in lower expression of various cancer- associated genes (CLEC1, DUSP6, FES and SAMSN1)." (PMID 28714904, 2017). "Although initial evaluations of the potential of BRD9‐based targeted therapy have been explored in the clinical application of a small number of cancer types, more detailed study of the diagnostic and prognostic potential, as well as the detailed biological mechanism of BRD9 remains unreported." (PMID 38303608, 2024). "BRD9 demonstrates recognition and binding capabilities for acetylated or butylated lysine residues, leading to post-translational modifications implicated in various diseases, especially cancer." (PMID 38543178, 2024). "Interestingly, in Smarcb1 deficient cancer entities, ncBAF specific subunit BRD9 was identified as being essential for tumour cell proliferation, further supporting the idea that the ncBAF ensures cells’ survival by taking over cBAF functions." (PMID 35456033, 2022). "In the TCGA cohort, there is evidence suggesting that BRD9 is more likely to be mutated in higher Gleason grades and more advanced cancer, and screening these groups and targeting BRD9 in patients with mutations may be a viable therapeutic strategy." (PMID 34944438, 2021). "Given the exquisite sensitivity of SMARCB1-deficient cells to BRD9 inhibition, we hypothesized that BRD9/BRG1 peaks would occupy activate promoters associated with the hallmarks of cancer." (PMID 34071089, 2021).
cancer (continued). "In addition, there appears to be a connection between splicing factor protein SF3B1 mutations and BRD9 degradation in cancers like myeloid leukemia, lymphoid leukemia, and uveal melanoma." (PMID 33143733, 2020). "Therefore, it will be important to test the efficacy of BRD9 targeting in other cancers with BAF complex mutations." (PMID 30431433, 2018). "Performing a comprehensive analysis of BRD9 with potential clinical value and evaluation of its association with prognosis and potential molecular mechanisms can offer fresh insights into our understanding of tumourigenesis and the advancement of cancer therapies." (PMID 38303608, 2024). "A sgRNA-resistant SMARCA4 expression construct in which the SMARCA4 bromodomain is replaced with the bromodomain of BRD9 (SMARCA4res-BDBRD9) was designed to determine whether acute degradation of SMARCA4 represents a therapeutic approach against SMARCA2-deficient cancers." (PMID 31406271, 2019). "However, the discovery of EZH2 inhibitors and BRD9 inhibitors as possible therapeutic approaches for some cancers with BAF subunit mutations, illustrates why the comprehension of the precise mechanism by which subunit mutations result in tumour growth, is so important." (PMID 30898143, 2019). "BRD9 is a key protein in chromatin regulatory systems, participating in BAF complex functional regulation, playing crucial roles in cancers like synovial sarcoma and SMARCB1‐deficient tumors." (PMID 41049269, 2025). "The role of BRD9 in oncogenesis appears two-sided since BRD9 has been shown to either drive or suppress cancer phenotypes." (PMID 39261602, 2024). "This research is expected to provide new insights into the inhibitory mechanism of 82I and POJ on BRD9 and offer a theoretical foundation for the development of cancer treatment strategies targeting BRD9." (PMID 39124901, 2024). "The STAT2 signaling pathway, which plays a role in the immune response that includes cancer initiation and inflammation, was identified as a major upregulated pathway in response to doxycycline-induced BRD9 KD coupled with pomalidomide." (PMID 38610997, 2024). "BRD9 is expressed in a variety of cancer forms, hence, its inhibition holds particular significance in cancer research." (PMID 38543178, 2024). "We employed EPIC, MCPCOUNTER, XCELL and TIDE algorithms to investigate the potential link between the prevalence of CAFs and BRD9 expression in various cancer types within the TCGA database." (PMID 38303608, 2024). "This research is expected to provide new insights into the inhibitory mechanism of 82I and POJ on BRD9 and offers a theoretical foundation for development of cancer treatment strategies targeting BRD9." (PMID 39124901, 2024). "Among the 63 possible therapeutic target HAMPs found by integrated genome analysis, BRD9 has the highest overall recurrent score, which suggests that this protein is a very attractive target for cancer therapy." (PMID 38543178, 2024). "Expression profile of BRD9 in each TCGA cohort was treated as training set, and microarray dataset from Gene Expression Omnibus(GEO) corresponding to each cancer type was used as independent validation." (PMID 38303608, 2024). "There have been some studies showing that BRD9 as a target for anticancer drugs has potential clinical value in some specific cancer types." (PMID 38303608, 2024). "The correlations between BRD9 expression and the expression of these immune checkpoint‐related genes were analysed for 33 cancer types in TCGA database." (PMID 38303608, 2024). "Our pan‐cancer analysis of BRD9 provides a comprehensive framework perspective for further studies and the development of BRD9‐based targeted therapies for a variety of different diseases." (PMID 38303608, 2024). "In detail, BRD9 was located together with other known cancer dependencies, including PIK3R1, EZH2, and FBXW7, whereas SF3B1 had a very high efficacy but low selectivity." (PMID 39261602, 2024).
cancer (continued). "Inhibition of BRD9 activity plays an important role in the treatment of certain cancers, making it a potential target for anticancer drugs." (PMID 39124901, 2024). "Positive phosphorylation sites were illustrated in a schematic diagram of the BRD9 protein, comparing normal tissues to primary tumour tissues, and variations in BRD9 phosphorylation levels were depicted using box plots for different cancer types." (PMID 38303608, 2024). "We used various bioinformatics tools to generate a comprehensive, pan‐cancer analyses of BRD9 expression in multiple disease types described in The Cancer Genome Atlas (TCGA)." (PMID 38303608, 2024). "For example, ASOs have been effectively used to modify the alternative splicing of BRD9 in certain SF3B mutant cancers, leading to the restoration of BRD9 protein expression and a subsequent decrease in tumor size." (PMID 38539439, 2024). "Numerous research studies have consistently disclosed BRD9’s crucial oncogenic role in various cancer types, influencing tumor proliferation and differentiation." (PMID 38543178, 2024). "TIDE algorithm was employed to investigate the potential connection between the predominance of MDSCs and BRD9 expression across different cancer types within the TCGA database." (PMID 38303608, 2024). "Recently, significant success has been achieved in designing and identifying BRD9 inhibitors with benefits impacting multiple types of cancer." (PMID 38255982, 2024). "Preclinical studies have demonstrated the efficacy of BRD9 inhibition in suppressing tumor growth, enhancing the sensitivity of cancer cells to chemotherapy, and modulating immune responses in inflammatory conditions." (PMID 38543178, 2024). "In cancer, degradation of BRD9-induced downregulation of oncogenic transcriptional programs inhibited tumor progression in vivo only in a synovial subtype of sarcomas (and synovial sarcoma is concerned with stem cell malignancy)." (PMID 36674511, 2023). "Motivated by recent discovery of disrupted expression of BRD9, an essential component of ncBAF, in multiple cancers, including clonal hematopoietic disorders, we evaluate here the role of BRD9 in normal and malignant HSCs." (PMID 38102116, 2023). "Studies have shown that BRD9 is preferentially used by cancers harboring SMARCB1 abnormalities, such as malignant rhabdoid tumors and several specific types of sarcomas." (PMID 36733714, 2023). "To determine if BRD9 inhibition influenced multiciliation, we established a new inducible system to generate MCCs in human cancer cells based on previous work using induced pluripotent stem cells." (PMID 36932059, 2023). "BRD9 is frequently amplified in cancer and is a vulnerability in cancer cells with inactivation of SMARCB1 or tumors having an oncogenic SS18-SSX fusion." (PMID 35323214, 2022). "There is strong evidence that mutations of splicing components SRSF2 and SF3B1 cause cancer in part by enhancing the inclusion of pseudoexons with in-frame stop codons for two genes EZH2 and BRD9, respectively." (PMID 35188075, 2022). "The interaction of BRD9 with SWI/SNF complexes represents an area of much current interest for cancer treatment." (PMID 36297001, 2022). "BRD9 has been considered an essential drug target for cancer, inflammatory diseases, and metabolic disorders." (PMID 36362300, 2022). "Studies have demonstrated that BRD9 plays an oncogenic role in multiple cancer types, by regulating tumor cell growth." (PMID 35883603, 2022). "BRD9 warrants further investigation in ERG fusion positive cancers and possibly co-targeted with ERG inhibition, as ERG depends on BAF complexes for its epithelial to mesenchymal transition (EMT)." (PMID 34944438, 2021). "Our data show that BRD9 mutations are less prevalent in ERG fusion positive cancers, in line with the literature suggesting these cancers are less likely to have mutated SWI/SNF complexes." (PMID 34944438, 2021).